MOGAT1 (monoacylglycerol O-acyltransferase 1)
Description:
Involved in glycerolipid synthesis and lipid metabolism. Catalyzes the formation of diacylglycerol, the precursor of triacylglycerol, by transferring the acyl chain of a fatty acyl-CoA to a monoacylglycerol, mainly at the sn-1 or sn-3 positions. It uses both sn-2-monoacylglycerol (2-acylglycerol) and sn-1-monoacylglycerol (1-acyl-sn-glycerol) equally well as substrates, and uses sn-3-monoacylglycerol (3-acyl-sn-glycerol) with lower efficiency. Probably not involved in absorption of dietary fat in the small intestine.
Synonyms: MGAT1; DGAT2L1; DGAT2L
Tractability: Antibody: UniProt predicts a signal peptide or a membrane-spanning region.
Gene: Protein-coding gene on chromosome 2 (222,671,658 to 222,709,930, forward strand). Ensembl gene ENSG00000124003.
Subcellular location: Endoplasmic reticulum membrane
Subcellular location (Human Protein Atlas): Cytosol; Endoplasmic reticulum
Pathways (Reactome):
Metabolism: Triglyceride biosynthesis
Gene Ontology:
Molecular function: 2-acylglycerol O-acyltransferase activity; acyltransferase activity, transferring groups other than amino-acyl groups; diacylglycerol O-acyltransferase activity
Biological process: diacylglycerol biosynthetic process; triglyceride biosynthetic process
Cellular component: endoplasmic reticulum membrane; endoplasmic reticulum; membrane
Genetic constraint (gnomAD): Loss-of-function variants: 31 observed, 31.95 expected, observed/expected ratio (o/e) 0.97, 90% interval 0.73 to 1.31. The upper end of that interval is the gene's LOEUF score, 1.31, which puts it in group 5 of 6, group 1 being the genes least tolerant of losing a copy. Missense variants: 410 observed, 396.75 expected, observed/expected ratio (o/e) 1.03, 90% interval 0.95 to 1.12. Synonymous variants: 142 observed, 143.35 expected, observed/expected ratio (o/e) 0.99, 90% interval 0.86 to 1.14.
Homologues: Orthologues: chimpanzee MOGAT1 (98% identical), macaque MOGAT1 (92% identical), pig MOGAT1 (81% identical), dog MOGAT1 (80% identical), rabbit MOGAT1 (79% identical), mouse Mogat1 (73% identical), rat Mogat1 (72% identical), tropical clawed frog mogat1 (67% identical), guinea pig MOGAT1 (65% identical), Caenorhabditis elegans K07B1.4 (43% identical), zebrafish mogat3a (43% identical), Caenorhabditis elegans dgtr-1 (43% identical), and 5 more. Paralogues in human: MOGAT2 (53% identical), DGAT2 (50% identical), DGAT2L6 (44% identical), MOGAT3 (43% identical), AWAT1 (41% identical), AWAT2 (39% identical).
Diseases named in the same sentence as MOGAT1 in open-access papers:
MOGAT1 is named in the same sentence as 17 diseases in open-access papers, as found by Europe PMC text mining. Sharing a sentence is not in itself a finding about the gene and the disease. The quoted sentences say what the papers report.
Hepatic steatosis (14 papers, 2013 to 2025). Steatosis is a term used to denote lipid accumulation within hepatocytes. "In thymectomized mice, we observed an upregulation of novel genes that have demonstrated to either be causal (Mogat1, Pklr) or associated with liver steatosis (Serpina7, and Hcn3)." (PMID 41034932, 2025). "Genistein also attenuated hepatic steatosis by reducing the PPARγ target gene monoacylglycerol O-acyltransferase 1, mRNA level in apolipoprotein E-deficient (ApoE(−/−)) mice fed a HF diet." (PMID 33383845, 2020). "Knockdown of Mogat1 in liver leads to significant reduction in hepatic steatosis in both HFD‐fed mice and ob/ob mice." (PMID 38506086, 2024). "Mogat1 plays a role in TG metabolism in the liver, fat absorption in the gastrointestinal tract, and the early development of type 2 diabetes, hepatic steatosis, and obesity." (PMID 39275255, 2024). "PPARγ induces hepatic steatosis through the expression of monoacylglycerol O-acyltransferase 1 gene (MGAT 1), a target gene of PPARγ for TG synthesis, and induces inflammation in CAC." (PMID 37569481, 2023). "MOGAT1 is involved in converting monoacylglycerol to diacylglycerol, which was overexpressed in the livers of obese mice suffering from hepatic steatosis." (PMID 36558373, 2022). "Up regulation of Mogat1 conceivably mediates hepatic steatosis and insulin resistance through increasing intracellular diacylglycerol content, consistent with our results." (PMID 36348490, 2022). "A study reported that up-regulation of MOGAT1 gene can mediate hepatic steatosis by increasing intracellular diacylglycerol content." (PMID 31419940, 2019). "Recently, we reported that increased PPARγ2 expression is a major contributor to high-fat-diet-induced hepatic steatosis, demonstrating that monoacylglycerol O-acyltransferase 1 (MGAT1), a PPARγ-regulated enzyme, plays a critical role in lipid accumulation." (PMID 27404390, 2016). "However, it can be appreciated that the level of Mogat1 expression in the livers is several fold less when compared to tissues like the stomach or kidney and it is only upregulated in pathological conditions like hepatic steatosis." (PMID 27611931, 2016). "Though other cis-regulatory elements were also predicted in the Mogat1 promoter, in this study we focused on PPAR, which is known to be involved in hepatic steatosis and lipid accumulation." (PMID 27611931, 2016). "The absence of OPN reversed HFD-induced fatty liver, as shown by the reduction of lipogenic gene expression of Srebf1, Mogat1 and Dgat2 and TG accumulation in the liver." (PMID 24871103, 2014).
Obesity (7 papers, 2010 to 2024). Accumulation of substantial excess body fat. "Low levels of CIDEA are associated in mice with increased thermogenesis and protects from obesity, while Mogat1 is a critical genes essential for triacylglycerol biosynthesis." (PMID 36709356, 2023). "On an HFD, global Mogat1 deletion contributed to obesity, insulin sensitivity, and glucose intolerance." (PMID 37238090, 2023). "The expression of Mogat1 in the liver has been shown to remarkably increase in high-fat diet fed mice models, and its expression is induced by obesity through direct activation of PPARγ." (PMID 34835949, 2021). "In addition, adipose tissue MOGAT1 expression is greater in people with obesity who are metabolically normal than those who are metabolically abnormal." (PMID 29853530, 2018). "We sought to determine whether the expression of Mogat1 might be regulated in adipose tissue in mouse models of metabolically abnormal obesity." (PMID 29853530, 2018). "Besides the annotated body weight relevant genetic elements, such as QTL rs3662726, genes Mogat1, Igfbp2, and Cyp2c37, mgRF provided valuable hypotheses on putative, novel genetic elements and their interactions that are potentially important for body weight and obesity." (PMID 23505362, 2013).
Insulin resistance (6 papers, 2013 to 2025). Increased resistance towards insulin, that is, diminished effectiveness of insulin in reducing blood glucose levels. "Mogat1 is one of the enzymes converting monoacylglycerol to diacylglycerol, this phase being linked to the development of hepatic insulin resistance." (PMID 34835949, 2021). "In summary, we demonstrate that Mogat1 is robustly induced during adipocyte differentiation and expression of adipose tissue Mogat1 in mice and MOGAT1 in humans are suppressed in states of relative insulin resistance and increased lipolytic rates." (PMID 29853530, 2018). "Mice with overfeeding found that the up‐regulated expression of monoacylglycerol O‐acyltransferase (Mogat1) conceivably mediates insulin resistance, accompanied by the occupancies of H3K4me3, H3K27me3 and H3K9ac, which were significantly increased in the promoter of the Mogat1 gene." (PMID 40522008, 2025). "However, we did not detect evidence of insulin resistance in Adn-Mogat1−/− mice, which had less fat mass and lower blood glucose than WT controls." (PMID 29853530, 2018). "Similarly, C3H mice, which lack Pparγ expression in the liver, did not enhance hepatic Cd36, Fabp4, and Mogat1 expression on the SRD diet or in response to liver insulin perfusions, and furthermore, they did not develop hepatosteatosis and hepatic insulin resistance in response to the SRD." (PMID 26085100, 2015).
steatosis (3 papers, 2019 to 2022). Increased lipid within the cytoplasm of cells. "A liver-specific shRNA against Mogat1 protected the liver from steatosis in three different models." (PMID 32213983, 2020). "In a neonatal overfeeding mouse model, epigenetic programming of histone modifications at Monoacylglycerol O-acyltransferase 1 (Mogat1) locus was reported to link neonatal overnutrition with long-term hepatic insulin resistance and steatosis through increasing intracellular diacylglycerol content." (PMID 31849831, 2019). "Moreover, overexpression of Mogat1 promoted the TG synthesis, while knockdown of liver Mogat1 decreased body weight, improved insulin sensitivity, and alleviated hepatic lipid accumulation and steatosis in HFD-induced and genetic obese mice." (PMID 36012616, 2022).
COVID-19 (1 paper, 2021). A disease caused by infection with severe acute respiratory syndrome coronavirus 2. "A current report shows that diacylglycerols (DAG) is reduced in COVID-19 patients' plasma, which is consistent with our results that the key enzymes MOGAT1/2/3 for DAG synthesis are downregulated." (PMID 33314005, 2021).
diabetes (1 paper, 2016). "Mogat1 has also been reported in the livers of diet induced obese mice, ob/ob mice, in mouse models of diabetes like KKAy and db/db mice and in cultured murine hepatocytes." (PMID 27611931, 2016).
Genetic obesity (1 paper, 2018). "This is not completely unexpected and is consistent with our observation that there is a significant suppression of Mogat1 expression in mouse models associated with high rates of adipose tissue lipolytic activity, including fasting, β-adrenergic receptor activation, and genetic obesity." (PMID 29853530, 2018).
hepatoma (1 paper, 2016). "It is interesting to note that a normal mouse liver has very low levels of Mogat1 expression whereas rat hepatoma cells express Mogat1 at higher levels, though at this point the role of Mogat1 in these cells is unclear." (PMID 27611931, 2016). "Furthermore, when we amplified Mogat1 in 3T3-L1, CHO and HTC cells, only HTC, a rat hepatoma cell line, amplified Mogat1 which was verified by sequencing." (PMID 27611931, 2016).
nonalcoholic fatty liver disease (1 paper, 2019). "MOGAT1 gene is involved in the glycerolipid metabolism (ko00561), and codes the MGAT (monoacylglycerol acyltransferases) enzyme, which is active in human liver and its activity can represent a viable target for pharmacologic intervention to treat nonalcoholic fatty liver disease." (PMID 31419940, 2019).
salpingitis (1 paper, 2023). Acute or chronic inflammation of the fallopian tube. "In this study, HK2 and MOGAT1 were upregulated and CA4, CNTN3, and ACAN were downregulated in the CN-LPS group, suggesting that LPS-induced salpingitis caused abnormal lipid and sugar metabolism and altered the acid–base balance of the internal environment, degrading the extracellular matrix." (PMID 37978561, 2023).
infection (1 paper, 2021). The state of being infected such as from the introduction of a foreign agent such as serum, vaccine, antigenic substance or organism. "Monoacylglycerol acyltransferases (MOGATs), lipin phosphatidic acid phosphatases (LIPINs), and diacylglycerol acyltransferases (DGATs) are key enzymes in TAG biosynthesis, and all the three types of enzymes were downregulated upon infection, including MOGAT1/2/3, LPIN3, and DGAT1/2." (PMID 33314005, 2021).
tumor (1 paper, 2024). "Next, we observed MOGAT3, but not MOGAT1 or MOGAT2, markedly elevated in resistant PDX tumors and RKO EC-R cells compared with respective sensitive tumor cells." (PMID 39436710, 2024).
MOGAT1 also shares sentences with these, for which no sentence is quoted: cancer (1 paper); Glucose intolerance (1); ovarian carcinoma (1); overnutrition (1); type 2 diabetes (1).